RAC1 (Rac family small GTPase 1)
Diseases named in the same sentence as RAC1 in open-access papers (continued):
Sharing a sentence is not in itself a finding about the gene and the disease.
diabetes (42 papers, 2015 to 2025). "Epigenetic regulation of RAC1 appears to be implicated in metabolic diseases such as diabetes; and cancer and psychiatric disorders, such as depression and substance abuse." (PMID 40396280, 2024). "In diabetes, Dnmts and Tets are activated in the retina and its vasculature, and dynamic DNA methylation-hydroxymethylation at the promoters of Rac1 and matrix metalloproteinase 9 is associated with their activation and mitochondrial damage." (PMID 35733767, 2022). "Epigenetic modifications at Rac1 promoter are associated with its transcriptional activation in diabetes, and the promoter undergoes DNA methylation-hydroxymethylation." (PMID 34063353, 2021). "Rac1 is the cytosolic regulatory subunit of theNADPH oxidase (NOX) multicomponent system responsible for ROS generation.Rac1 signaling pathway is implicated in diabetes pathogenesis, mainlyby the generation of oxidative stress and islet dysfunction." (PMID 34236862, 2021). "Notably, many previous studies had attempted to elucidate the association between RAC1 and diabetes and the molecular mechanisms involved." (PMID 31915515, 2019). "Abnormal Rac1 signaling is involved in ROS production and inflammatory responses and reportedly linked to a number of debilitating human diseases, including cancer, diabetes, and kidney disorders." (PMID 29497040, 2018). "Thus in the present study, we described a podocyte-specific Rac1-deficient mouse strain and generated diabetes models in these mice, aiming to uncover a renoprotective and therapeutic role of cell-specific Rac1 deficiency in DN and related podocyte damage." (PMID 29497040, 2018). "Therefore, anomalous or dysfunctional RAC1 signalling is implicated in various human pathologic conditions, including neurodegenerative disorders, mental retardation and micro-and macrocephaly, epilepsy, cardiovascular diseases, diabetes and cancer." (PMID 40396280, 2024). "Moreover, we prioritized drug-targets such as melatonin, resveratrol, eugenol, lapatinib, geldanamycin and azathioprine which interacted with ESR1, ERBB2, HSP90AB1 and RAC1, respectively and shown associations in diabetes treatment in experimental models of T1D." (PMID 33841528, 2020). "These relations have been more extensively studied for mammalian Rac1 in the contexts of cancer development, immune response, brain functions, and diabetes, with some striking similarities observed for its fungal homologues." (PMID 38534316, 2024). "In experimental models of diabetes, pharmacological inhibition of Rac1 attenuates endothelial dysfunction and also reduces platelet hyperaggregation in patients with diabetes." (PMID 37566054, 2023). "In patients with diabetes, there is an activation of Rac-1, in addition to the aldosterone that is present." (PMID 37566054, 2023). "Diabetes activates Nox2 and Rac1, and Rac1-Nox2-ROS signaling is an early event in the pathogenesis of diabetic retinopathy." (PMID 36672234, 2023). "We have analyzed the roles of Rac1 in different bladder pathologies, including bacterial infections, diabetes-induced bladder dysfunctions and bladder cancers." (PMID 35740379, 2022). "Specifically, we have analyzed the role of Rac1 in bacterial infections of the bladder, in diabetes-induced bladder dysfunctions and in the various steps of bladder cancer (tumorigenesis, tumor progression, metastasis)." (PMID 35740379, 2022). "In diabetes, increased cytosolic ROS, generated by activation of Ras-related C3 botulinum toxin substrate 1 (Rac1)-NADPH oxidase 2 (Nox2)-activation of gelatinase matrix metalloproteinases in diabetes damage mitochondria in retinal capillaries." (PMID 35733767, 2022). "As the topic of regulation of Rho GTPases has beenwidely summarized recently, here we concentrateon selected inhibitors, directly targeting Rac1 and RhoA, as the connectionsof these with diabetes-related malfunctions are the most broadly reported." (PMID 34236862, 2021).
diabetes (continued). "We demonstrate that diabetes increases the recruitment of Suv39H1 at Rac1 promoter, which assists in the recruitment of Dnmt1, initiating an active DNA methylation-hydroxymethylation and transcriptional activation." (PMID 34238980, 2021). "In diabetes, Rac1 is functionally active, and while its binding with guanine exchange factors (GEFs) is increased and with its guanine dissociation inhibitor (GDIs) is decreased." (PMID 34238980, 2021). "One of the integral proteins in the assembly of Nox2 holoenzyme, Rac1, is also activated in diabetes, and due to epigenetic modifications its gene transcripts are upregulated." (PMID 34063353, 2021). "In diabetes, the binding of histone trimethyltransferase, Suv39H1, is increased at Rac1 promoter, and increase in H3K9me3 facilitates the recruitment of the DNA methylation machinery." (PMID 34063353, 2021). "While expression or activity of Rab members tends tobe downregulated under conditions that favor the development of diabetes,overactivated RhoA and Rac1 are involved in many of the pathologiesobserved in T2D individuals." (PMID 34236862, 2021). "Diabetes also upregulates the gene expression of Rac1, and recent research has shown that gene expression can also be regulated by epigenetic modifications, the modifications that regulate expression of a gene without altering its DNA sequence." (PMID 34063353, 2021). "Diabetes also transcriptionally activates Rac1, and its gene expression is elevated in the retina and its capillary cells." (PMID 34238980, 2021). "Regulation of Suv39H1 by its siRNA prevented diabetes-induced upregulation of Rac1 transcription; Rac1 gene transcripts in diabetic mice receiving Suv39H1-siRNA were not significantly different from those obtained from normal mice." (PMID 34238980, 2021). "In diabetes, Rac1 is functionally activated in the retina and its vasculature, and, via Nox2-ROS, contributes to mitochondrial damage and the development of retinopathy." (PMID 31277234, 2019). "Pharmacological investigations involving Rac1 inhibitors have suggested Tiam1 (NSC23766), Vav2 (Ehop-016) and SoS1 as GEFs involved in sustained activation of Rac1 in the retina in diabetes." (PMID 31277234, 2019). "The following sections discuss how Rac1 regulation is altered in diabetes, and its role in the development of diabetic retinopathy." (PMID 31277234, 2019). "Since Rac1 is also transcriptionally activated in diabetes, and epigenetic modifications modulate its transcriptional activation, targeting the enzymes responsible for such modifications provides another opportunity to regulate Rac1 activation." (PMID 31277234, 2019). "In diabetes, the binding of both Dnmt1 and Tet2 is increased at its promoter, suggesting an active methylation-hydroxymethylation process of the Rac1 promoter." (PMID 31277234, 2019). "We have shown that the inhibition of Vav2 by its pharmacological inhibitor EHop, in addition to regulating diabetes-induced activation of Rac1-Nox2, also prevents mitochondrial damage, vascular leakage and capillary cell apoptosis." (PMID 31277234, 2019). "The multicomponent cytosolic Nox2 has an obligatory component, Ras-related C3 botulinum toxin substrate 1 (Rac1); in diabetes, Rac1 is functionally and transcriptionally active." (PMID 30347077, 2018). "Rac1 is also activated by diabetes mellitus and high vessel distension pressure, suggesting its potential involvement in venous graft failure." (PMID 28246076, 2017). "The present data provide novel insight that Rac1 activation is involved in BRB breakdown in diabetes." (PMID 25452781, 2015). "Rac1 activation increased by 55.6, 77.6 and 89.8%, respectively (each P<0.05), in the retinas at four, eight and 12 weeks after the induction of diabetes compared with that in the controls." (PMID 25452781, 2015). "Diabetes also affects the epigenetics of Ras-related C3 botulinum toxin substrate 1 (Rac1)." (PMID 40725425, 2025).
diabetes (continued). "In other tissues, the complex may enhance rather than prevent apoptosis, as inhibition or depletion of Rac1 in mouse models of diabetes promoted survival and alleviated mitochondria-related oxidative stress." (PMID 38534316, 2024). "Addition of hyperlipidemia in a hyperglycemic milieu, which mimics type 2 diabetes, further exacerbates Rac1–Nox2–ROS activation, and as the duration of diabetes increases, mitochondrial damage worsens, ultimately leading to the capillary cell loss and the development of diabetic retinopathy." (PMID 36202842, 2022). "However, the inhibitory effect of apophynin on NOX and Rac1 expression can improve diabetes-related atrial remodeling." (PMID 36139819, 2022). "Interestingly, the expression of Rac1 in bladder tissue is increased not only due to the diabetes context, but it is also enhanced mechanically through the induced and cyclic hydrodynamic pressure exerted on bladder smooth muscle cells." (PMID 35740379, 2022). "In addition, diabetes also facilitates retinal Rac1 to undergo dynamic DNA methylation-hydroxymethylation, resulting in its transcriptional activation." (PMID 34238980, 2021). "In diabetes, both DNA methylating (Dnmts) and hydroxymethylating/demethylating (ten-eleven translocase, Tets) enzymes are activated in the retinal vasculature, and Rac1 promoter undergoes dynamic DNA methylation." (PMID 34063353, 2021). "In diabetes, GEF, T cell lymphoma invasion and metastasis (Tiam1), is shown to be critical in orchestrating Rac1 activation; activation of Tiam1-Rac1-Nox2 signaling axis, an early event in the pathogenesis of diabetes, leads to mitochondrial damage and accelerated capillary cell apoptosis." (PMID 31277234, 2019). "In the present study, we described a podocyte-specific Rac1-deficient transgenic mouse strain, which exhibited neither embryonic lethality nor spontaneous proteinuria or diabetes." (PMID 29497040, 2018). "Our aim was to investigate the role of epigenetics in Rac1 regulation in diabetes." (PMID 30347077, 2018). "Similarly, in mouse retinal microvessels, Dnmt1-siRNA ameliorated diabetes-induced increase in Rac1 transcripts and activity, and decreased ROS levels." (PMID 30347077, 2018). "High glucose-induced increase in Rac1-ROS can be seen within 6 hours in retinal endothelial cells and within 15 days of diabetes in rodents, and increase in mitochondrial damage and capillary cell apoptosis within 96 hours in cells and approximately 6 months of diabetes in mice." (PMID 30347077, 2018). "By generating diabetes models in these TG diabetic mice as well as their littermate controls, we were able to show that podocyte-specific Rac1 depletion might be of therapeutic importance to the pathogenesis of DN." (PMID 29497040, 2018). "Importantly, we previously found that Rac1 is activated in response to diabetes mellitus and mechanical stress in endothelial cells and is required for the development of endothelial dysfunction under these conditions." (PMID 28246076, 2017). "In our experiments, we demonstrated upregulation of Rac1 in diabetes." (PMID 28388570, 2017). "Furthermore, we investigated the effect of RAC1 SNPs on ERSD risk according to smoking status, diabetes status, and hypertension status." (PMID 26841219, 2016). "This study used a streptozotocin (STZ)-induced rat model of diabetes to investigate whether Ras-related C3 botulinum toxin substrate 1 (Rac1) was involved in the pathogenesis of diabetic retinopathy." (PMID 25452781, 2015). "Rac1 may be involved in the diabetes-induced damage and/or alterations to the blood-retinal barrier through changes in VE-cadherin and β-catenin expression." (PMID 25452781, 2015). "Furthermore, several studies have identified the key role for Rac1 GTPase in the regulation of high-glucose- and diabetes-induced VSMC proliferation." (PMID 25918730, 2015). "In conclusion, diabetes affects the expression of Rac1 in the retina." (PMID 25452781, 2015).
diabetes (continued). "Herein, we tested the hypothesis that activation of p38 MAP kinase, a stress kinase, represents the downstream signaling event to Rac1-Nox2 activation in diabetes-induced metabolic stress leading to capillary cell apoptosis." (PMID 25967961, 2015). "Although how ceramides activate DNA methylation–hydroxymethylation machinery is not clear, the possible mechanism could be that elevated ceramides levels in diabetes, via increasing ROS, activate DNA methylation–hydroxymethylation machinery, and increase Rac1 transcription." (PMID 36202842, 2022). "Antioxidant effect of atorvastatin in diabetes may be mediated through inhibition of Rac-1 and geranylgeranyl pyrophosphate (GGPP), induction of heme oxygenase, interference with NAD(P)H oxidase expression and activity and antagonization of the pro-oxidant effect of angiotensin II." (PMID 34400938, 2021). "Therefore, we believed that miR-574-3p and RAC1 might be potential biomarkers or new therapeutic targets for diabetes." (PMID 31915515, 2019). "However, amelioration of diabetes-induced increased NF-κB binding at the Rac1 promoter by both Dnmt and Tet inhibitors, observed in the present study, clearly suggests that dynamic CpG methylation is playing a critical role in the regulation of binding of this transcription factor." (PMID 30347077, 2018). "These in vivo and in vitro observations demonstrated Rac1 depletion benefited diabetic podocytes through a major and early attenuation on plasticity of podocyte cytoskeleton via preserving SDs and FPs both structurally and functionally in the challenge of diabetes." (PMID 29497040, 2018). "Administration of SPT-siRNA at the time of induction of diabetes in Diab and HF-SD groups (Diab/SPT-si and HF-SD/SPT-si groups) prevented activation of Rac1–Nox2 and increase in ROS levels." (PMID 36202842, 2022). "The mRNA RAC1 harbored 37 genes and ranked first in CNC analysis, which has been explored in diabetes, diabetic retinopathy, and so on." (PMID 35082751, 2021). "Thus, while the Rho GTPases Cdc42 and Rac1 are critical for insulin secretion, pathological hyperactivation of Rac1 and RhoA negatively affects β cell function during times of stress and may thus be targets for preventing β cell failure in diabetes." (PMID 31075957, 2019). "The present results demonstrated that increased Rac1 activity occurred in the retina at four, eight and 12 weeks after the induction of diabetes by STZ, although Rac1 mRNA levels remained unchanged." (PMID 25452781, 2015). "Prominent genes were RHOA, AKT1, RAC1, MDM2, CDKN1A, and VEGFA, which play important roles in TGF-beta and mTOR signaling (KEGG database), signaling by Wnt and by NOTCH (Reactome database), and in complications in diabetes mellitus (DisGeNET database)." (PMID 35742976, 2022). "Moreover, after a 16-week duration of diabetes, Pggt1bΔ/Δ mice exhibited lower α-smooth muscle actin (α-SMA) and nitrotyrosine level, Rac1 activity, p47phox and NOXO1 expression, and phospho-ERK1/2 and phosphor-JNK content than wild-type mice." (PMID 32851097, 2020). "In vivo, diabetic wild-type mice exhibited a remarkably higher Rac1 activity than nondiabetic wild-type, whereas a 16-week duration of diabetes had no obvious effect on aortic Rac1 activity in Pggt1bΔ/Δ mice." (PMID 32851097, 2020). "The results showed that the level of Rac1 mRNA expression was not increased in the diabetic retinas at four, eight and 12 weeks after induction of diabetes compared with that in the controls." (PMID 25452781, 2015). "Last but not least, unraveling of the molecular basis of RAC1 regulation may aid in understanding a variety of diseases with the implication of RAC1 deregulation and dysfunction, including atherosclerosis, diabetes and cancer." (PMID 34830380, 2021).
cervical carcinoma (33 papers, 2008 to 2025). A carcinoma arising from either the exocervical squamous epithelium or the endocervical glandular epithelium. "Newly discovered tumors (such as cervical cancer) are associated with abnormal Rac1-mediated signaling pathways." (PMID 35847360, 2022). "Rab11 regulates transport from recycling endosomes to the plasma membrane, and it has been associated, together with Rac1, to colorectal carcinoma and cervical cancer, where it regulates tumor progression and metastasis through two different processes, collective cell migration and hypoxia." (PMID 31035701, 2019). "Further Tiam1, a known oncogene is dysregulated in NSCLC, endometrial, colorectal, pancreatic, and cervical cancer and is known to activate both Rac-1 and Cdc42." (PMID 37024613, 2023). "MCAK has been shown to be associated with the migration capacity of endothelial, epithelial and cervical carcinoma cells by regulating the polarization of MT growth and the FA turnover depending on RAC-1." (PMID 34830827, 2021). "Overexpression of SH3-domain-binding protein-1 (SH3BP1) promotes invasion, migration and chemoresistance of cervical cancer cells through increasing the activity of Rac1 and WAVE2." (PMID 34572403, 2021). "Small GTPases of the Rho family have been studied mainly on cervical cancer cell lines and RhoA, Rac1, and Cdc42 are the best characterized." (PMID 32443784, 2020). "Chemical inhibition of Rac1 with NSC23766 reduced cellular proliferation of cervical cancer derived (C33A, SiHa) cell lines." (PMID 32443784, 2020). "A study showed that Rac1 plays an important role in the regulation of apoptosis in cervical cancer cells, and its reduction can potentially increase chemosensitivity to cisplatin." (PMID 32443784, 2020). "Rac1-driven activation of STAT3 therefore was shown to stimulate both the proliferation and survival of HPV positive cervical cancer cells, thus highlighting a further example of Rac1 driving upstream activation of STAT3 in cancer." (PMID 32915198, 2020). "The expression level of Rac1 and RhoA were found to be increased in several cancers including cervical cancer." (PMID 31870092, 2019). "More interestingly, RAC1 as the paralog of RAC3 was reported to play an important role in cervical cancer progression." (PMID 31133010, 2019). "We also noted that blockade of Rac1 function reduced AKT dual phosphorylation either in cells expressing HPV18 E6 in isolation or in HPV positive cervical cancer cells." (PMID 31226168, 2019). "As has been described previously in HeLa cervical carcinoma cells, supervillin knockdown with RNAi #2 or #3 decreased Rac1 loading in normoxia." (PMID 29954442, 2018). "To evaluate the silencing activity of our polyplexes consisting of either Long or Short PGAamine and siRNA on human HeLa cervical carcinoma cells, we investigated the Rac1 expression using a psiCHECK reporter assay." (PMID 30966582, 2018). "Recently, DDX3 was shown to promote invasive behavior via Rac1-mediated Δ-catenin activation in cervical cancer and neuroblastoma cells." (PMID 27007150, 2016). "We observed a strong nuclear staining for RAP1 in CIN 2/3 samples, as previously reported in oropharyngeal SCC cell lines and human oral cancer specimens, and for other small GTPases, such as RHO and RAC1, in premalignant lesions and cervical cancer." (PMID 25856570, 2015). "Rac1 is expressed in the nucleus of epithelial cells in SILs and cervical cancer cell lines, and chemical inhibition of Rac1 reduces cellular proliferation." (PMID 22443139, 2012). "Rac1 is expressed in the nucleus of cervical premalignant-lesions and cervical cancer derived cells lines." (PMID 22443139, 2012). "In this study we analyzed the expression of the GTPases Rac1, RhoA, Cdc42, and the Rho-GEFs, Tiam1 and beta-Pix, in cervical pre-malignant lesions and cervical cancer cell lines." (PMID 22443139, 2012).